LINC00242 (long independently transcribed non-coding RNA 242)
Synonyms: C6orf122; NCRNA00242; FLJ31451; dJ266L20.5
Gene: Long non-coding RNA gene on chromosome 6 (169,788,790 to 169,799,549, reverse strand). Ensembl gene ENSG00000229214.
Diseases named in the same sentence as LINC00242 in open-access papers:
LINC00242 is named in the same sentence as 1 disease in open-access papers, as found by Europe PMC text mining. Sharing a sentence is not in itself a finding about the gene and the disease. The quoted sentences say what the papers report.
cancer (1 paper, 2021). A tumor composed of atypical neoplastic, often pleomorphic cells that invade other tissues. "LINC01436 and LINC00242 appear to render cancer cell to progression." (PMID 34285140, 2021). "The discrepancy of LINC00242 level may arise from different cancer types." (PMID 34285140, 2021).